AGRP (agouti related neuropeptide)
Diseases named in the same sentence as AGRP in open-access papers (continued):
Sharing a sentence is not in itself a finding about the gene and the disease.
anorexia nervosa (10 papers, 2011 to 2024). A disorder most often seen in adolescent females characterized by a refusal to maintain a minimally normal body weight, an intense fear of gaining weight, a disturbance in body image, and, in postmenarcheal females, the development of amenorrhea. "Emerging evidence points to the importance of hypothalamic agouti-related peptide (AgRP) neurons in anorexia nervosa, but the underlying molecular mechanisms linking AgRP neurons to this illness have remained ill-defined." (PMID 37036983, 2023). "The purpose of this review is to underline the potential role of AgRP neurons and ghrelin signaling in both the metabolic and behavioral changes observed in anorexia nervosa." (PMID 31998738, 2019). "Variants in the AgRP gene were found to be associated with anorexia nervosa and low BMI." (PMID 40656109, 2024). "Interestingly, individuals diagnosed with the eating disorder anorexia nervosa (AN) have increased circulating levels of AgRP, and a polymorphism in the coding region of AgRP is associated with AN." (PMID 23638159, 2013). "Other behavioural phenotypes of anorexia nervosa are likely to be influenced by the activity of AgRP neurons." (PMID 40656109, 2024). "In another study, reward association learning, studied as a measure of cognitive flexibility in adolescent patients with anorexia nervosa, was correlated with abnormal circulating levels of AgRP." (PMID 40656109, 2024). "Adolescent mice with anorexia nervosa display cognitive decline, and central inhibition of agouti-related peptide (AgRP) and neuropeptide Y (NPY) reverses the cognitive decline." (PMID 37168929, 2023). "AgRP signaling can be a new therapeutic target for cognitive decline in occlusal disharmony and anorexia nervosa." (PMID 37168929, 2023). "Although these data suggest that AgRP neurons may be a key neuronal target for therapeutic interventions related to symptoms of anorexia nervosa, further explorations are needed." (PMID 40656109, 2024). "In humans, data involving AgRP in symptoms of anorexia nervosa are still sparse." (PMID 40656109, 2024). "These authors suggested that elevated plasma AgRP may be related to energy homeostasis disturbances in anorexia nervosa." (PMID 26758700, 2016). "It has been reported that plasma levels of AgRP were elevated in anorexia nervosa, while plasma alpha-MSH levels were not significantly different in this study." (PMID 29147253, 2011).
Hyperglycemia (8 papers, 2018 to 2025). An increased concentration of glucose in the blood. "We also report that in Lepob/ob mice, normalization of hyperglycemia by AgRP neuron inactivation was associated with markedly decreased plasma insulin levels." (PMID 40371641, 2025). "Increased activity of NPY/AgRP neurons in the hypothalamic arcuate nucleus (ARC) is implicated in the pathogenesis of hyperglycemia in these animals, and the ARC is a key brain area for the antidiabetic action of FGF1." (PMID 35917179, 2022). "Conversely, specific inhibition of GABAArc neurons causes a leptin-mimicking effect on reducing T1D hyperglycemia, while inhibiting AgRP neurons has a much more attenuated effect." (PMID 33976218, 2021). "In contrast to POMC neurons, deleting of Lepr in AgRP neurons produces hyperphagia and hyperglycemia, resulting in massive weight gain that reaches about 80% of the weight observed in db/db mice, suggesting AgRP neurons play important roles in mediating leptin’s effects on energy balance." (PMID 38027481, 2023). "Blockade of ghrelin action during this period increases α‐MSH and AgRP fiber density in the PVN, DMH, and LHA, ultimately resulting in increased body weight gain and hyperglycemia." (PMID 40474775, 2025). "In the current work we report not only that hyperglycemia is normalized comparably by icv FGF1 and AgRP neuron inactivation, but that in each case the effects are sustained for weeks or months." (PMID 40371641, 2025).
Hypoglycemia (7 papers, 2015 to 2025). A decreased concentration of glucose in the blood. "This was associated with reduced activation by hypoglycemia of AgRP neurons as assessed by c-Fos immunostaining, patch clamp analysis, and in vivo fiber photometry; and with defective activation of the vagal nerve." (PMID 36180454, 2022). "Two studies claimed that Irak4 (Interleukin-1 receptor associated kinase-4) controls hypoglycemia-induced glucagon secretion by modulating hypothalamic Il-1β signaling, and Agpat5 activation in AgRP (agouti-related protein) neurons leads to hypoglycemia-induced glucagon secretion." (PMID 37764697, 2023). "We demonstrated that Agpat5 inactivation in AgRP neurons led to reduced hypoglycemia-induced glucagon secretion." (PMID 36180454, 2022). "The role of Agpat5 is, thus, to ensure that AgRP neurons respond faithfully to developing hypoglycemia." (PMID 36180454, 2022). "Thus, inactivation of Agpat5 led to a reduction in the number of AgRP neurons that can be activated by hypoglycemia as detected by c-Fos staining, patch clamp analysis, and in vivo intracellular Ca2+ recordings." (PMID 36180454, 2022). "Thus, reduced AgRP activation by hypoglycemia in AgRPAgpat5KO mice led to impaired vagal nerve firing and reduced glucagon secretion." (PMID 36180454, 2022). "Also, c-Fos immunolabelling and electrophysiological recordings both showed that hypoglycemia activated a lower number of AgRP neurons in AgRPAgpat5KO than in control mice." (PMID 36180454, 2022). "Just recently, acute insulin administration in mice was shown to induce both, hypothalamic AgRP expression and microglia activation suggesting a role for microglial cells in close vicinity to orexigenic neurons in facilitating the release of hunger signals to counteract hypoglycemia." (PMID 31572115, 2019). "This work extends the orchestration of the metabolic adaptations to energy deficit by AGRP neurons to include a suppression of peripheral glucose uptake, which may serve as a glucose sparing process to protect the brain from hypoglycemia in conditions of low energy availability." (PMID 28532548, 2017). "In agouti-related peptide (AgRP) neurons of the ARC, an alternate mechanism for hypoglycemia sensing is active." (PMID 36180454, 2022). "We speculate that the normal glucose level present in control animals (per definition) is robustly defended by a number of other systems and mechanisms, such that the presumed reduction in AgRP neuronal activity caused by the loss of glutamate action via NMDARs does not cause hypoglycemia." (PMID 26500840, 2015). "An intriguing observation is that inactivation of Agpat5 reduces the number of AgRP neurons activated by hypoglycemia without changing the electrophysiological properties of the remaining GI neurons and without reducing the total number of AgRP neurons." (PMID 36180454, 2022).
overnutrition (7 papers, 2013 to 2026). An imbalanced nutritional status resulting from excessive intake of nutrients. "Maternal obesity, overnutrition, or inflammation can durably alter AgRP and POMC connectivity through microglial activation and impaired perineuronal net (PNN) maturation, establishing a “metabolic memory” that predisposes offspring to lifelong glucose dysregulation." (PMID 41409607, 2025). "In a mouse model of diet-induced obesity (DIO), silent AgRP/NPY neurons presented with mitochondria that were increased in size and more elongated than those in wildtypes, demonstrating a role for mitochondrial fusion in AgRP neuronal response to overnutrition." (PMID 33240218, 2020). "Overnutrition and age-related iron accumulation in arcuate nucleus neurons increase mitochondrial ROS production, triggering redox-dependent transcriptional reprogramming (e.g., FoxO1 activation and AgRP upregulation) and resetting hypothalamic metabolic set points." (PMID 41596490, 2026). "Hypothalamic AgRP and POMC are ‘yin/yang’ master regulators that promote/inhibit food intake, previous studies observed a higher ratio of AgRP/POMC expressing neurons in offspring raised by mothers with maternal overnutrition during pregnancy and/or lactation." (PMID 38493217, 2024). "Based on the inhibitory action of Zj7 on the expression of the orexigenic neuropeptides AgRP and NPY, we hypothesized that Zj7 reduces food intake, resulting in improved overnutrition-induced weight gain." (PMID 38570726, 2024). "This pathway has not been examined previously in AGRP neurons; instead, based on whole hypothalamus analysis, UPR has been primarily associated with overnutrition states and leptin resistance, as opposed to the energy-deficit condition examined here." (PMID 26329458, 2015).
Cachexia (5 papers, 2009 to 2026). Severe weight loss, wasting of muscle, loss of appetite, and general debility related to a chronic disease. "This idea is supported by the fact that in animal studies, agouti-related protein (AgRP), the endogenous inverse agonist at the MC-4 receptor, was found to affect two hallmark features of cachexia, i.e. to increase food intake and to reduce energy expenditure." (PMID 19295909, 2009). "Taken together, our data suggest that AgRP may play a role in preventing cancer-related cachexia development, which supports the hypothesis of possible clinical utility of AgRP agonists." (PMID 29147253, 2011). "Recently, it has been reported that central administration of agouti-related peptide (AgRP) might have protective effect against cachexia development in tumor-bearing mice." (PMID 29147253, 2011). "After the development of the signs and symptoms of cachexia (lethargy, decreased food intake, minimal grooming), we began ICV administration of AgRP." (PMID 33824339, 2021). "However, after the development of cachexia symptoms, mice receiving ICV AgRP treatment increased food intake compared to their vehicle-treated counterparts." (PMID 33824339, 2021). "Independently of feeding status, AA induced cachexia, in which modulation of mRNA expressions for appetite-regulating neuropeptides (NPY, AgRP, POMC, CART) in the arcuate nucleus (ARC) does not play a primary role." (PMID 20953376, 2010). "Therefore the upregulation of NPY/AgRP mRNA expression in the ARC is not surprising in arthritic rats, and reflects physiological response in cachexia." (PMID 20953376, 2010).
Hypertension (5 papers, 2012 to 2022). The presence of chronic increased pressure in the systemic arterial system. "Further elucidation of the mechanisms by which AgRP neurons sense the changes in fluid osmolarity and/or [Na+] could contribute to the prevention and treatment of hypertension and cardiovascular diseases." (PMID 35807782, 2022). "We previously reported that the deletion of phosphoinositide-dependent kinase-1 (PDK1) in AgRP neurons enhanced SNA, thereby exacerbating hypertension under high-salt feeding conditions." (PMID 35807782, 2022). "mRNA levels of AgRP and NPY in the hypothalamus and brainstem were not affected by any diet and/or hypertension." (PMID 27273815, 2016).
malnutrition (5 papers, 2014 to 2026). Inadequate nutrition resulting from poor diet, malabsorption, or abnormal nutrient distribution. "No significant group differences were found for AgRP and POMC, although AgRP tended to be lower and POMC higher in the malnutrition group." (PMID 41683201, 2026). "Changes in the relative expression of MC4R and AgRP mRNAs during long term malnutrition of rat indicate a stimulatory role of MC4R and AgRP in regulating energy balance in ARC of rat hypothalamus." (PMID 25317405, 2014). "Thus, in a situation of negative energy balance, such as the malnutrition observed in ALS, the expression of NPY and AgRP is normally increased and POMC expression decreased." (PMID 34638645, 2021).
Hyperinsulinemia (4 papers, 2018 to 2025). An increased concentration of insulin in the blood. "However, in the present study, removal of the AgRP peptide did not reverse the hyperinsulinemia or the effects on insulin signaling genes caused by chronic corticosterone." (PMID 30794724, 2019).
chronic kidney disease (3 papers, 2017 to 2022). Impairment of the renal function secondary to chronic kidney damage persisting for three or more months. "Central injection of AGRP can reduce muscle atrophy and systemic inflammation in rats with chronic kidney disease." (PMID 35428321, 2022). "Moreover, reduced muscle wasting was observed after administration of AgRP, the antagonist of MC4-R, in the animal model of chronic kidney disease (CKD)." (PMID 28358856, 2017).
Hepatic steatosis (3 papers, 2016 to 2025). Steatosis is a term used to denote lipid accumulation within hepatocytes. "This highlights the need to build an understanding of the role of chronic GCs acting on AgRP neurons which, at least in part, leads to the GC-induced hyperinsulinaemia and hepatic steatosis." (PMID 34215821, 2021). "The present study has demonstrated that GCs acting on AgRP neurons contribute to the Cort-induced hyperinsulinaemia and hepatic steatosis in female mice." (PMID 34215821, 2021). "Our data demonstrate that AgRP neurons have a role in mediating the effects of GCs on hepatic steatosis and insulin homeostasis." (PMID 34215821, 2021). "It seems likely that these changes contribute to the reductions in hepatic steatosis and hyperinsulinaemia in the AgRP-GR KO mice." (PMID 34215821, 2021).
Sepsis (3 papers, 2018 to 2026). Sepsis is defined as life-threatening organ dysfunction caused by a dysregulated host response to infection. "With respect to the beneficial effects of leptin administration during sepsis, it is possible to hypothesize that leptin acts on the excitability of the POMC and NPY/AgRP neurons." (PMID 30618812, 2018).
vitamin D deficiency (3 papers, 2012 to 2017). A nutritional condition produced by a deficiency of VITAMIN D in the diet, insufficient production of vitamin D in the skin, inadequate absorption of vitamin D from the diet, or abnormal conversion of vitamin D to its bioactive metabolites. "It has been suggested that vitamin D deficiency increases appetite and decreases energy consumption by stimulating Agouti Related Protein/Neuropeptide Y (AgRP/NPY) and suppressing the pro-Opiomelanocortin/Cocaine-Amphetamine-Regulated Transcription (POMC/CART) pathway." (PMID 29281967, 2017). "It is suggested, however, that vitamin D deficiency increases appetite and decreases energy consumption by stimulating Agouti Related Protein/ Neuropeptide Y (AgRP/NPY) and suppressing the pro-Opiomelanocortin/ Cocaine- Amphetamine- Regulated Transcription (POMC/CART) pathway." (PMID 23297844, 2013).
acromegaly (2 papers, 2021 to 2022). Acromegaly is an acquired disorder related to excessive production of growth hormone (GH) and characterized by progressive somatic disfigurement (mainly involving the face and extremities) and systemic manifestations. "Moreover, plasma AgRP levels are high in patients with acromegaly, and pharmacological or surgical treatment reduces both GH secretion and plasma AgRP concentration." (PMID 33440789, 2021).
autism (2 papers, 2023 to 2024). Persistent deficits in social interaction and communication and interaction as well as a markedly restricted repertoire of activity and interest as well as repetitive patterns of behavior. "Substantial literatures have shown that AgRP neurons are implicated in regulating core symptoms of autism beyond feeding." (PMID 38570876, 2024). "Notably, AgRP neurons are 5-hydroxytryptamine (5-HT) receptor-positive neurons, which are strongly associated with autism." (PMID 38570876, 2024). "The hypothalamic circuitry implicated by these data suggest impaired excitation of AgRP/NPY feedback inhibitory neurons may explain the increased aggression behavior found in genetic forms of autism." (PMID 36909588, 2023). "Thus, whether AgRP neurons are associated with the Shank3 deficiency-caused autism is still unknown." (PMID 38570876, 2024). "Our results unveil that p38α signaling in AgRP neurons plays a critical role in the development of autism, particularly in the SHANK3 pathway mutant-related population." (PMID 38570876, 2024). "Together, p38α in POMC and AgRP neurons play distinct roles in regulating autism-like behaviors." (PMID 38570876, 2024). "Therefore, further experiments are required to identify whether the activity of p38α in AgRP neurons modulates all types of autism." (PMID 38570876, 2024).
endotoxemia (2 papers, 2017 to 2022). "In the endotoxemia group in our study, the hypothalamic inflammation was also related to the alterations of the mRNA expression of POMC and AgRP, which was consistent with former studies." (PMID 28358856, 2017).
hyperlipidemia (2 papers, 2022 to 2023). "Proopiomelanocortin (POMC), an appetite-inhibiting neuropeptide, is decreased by increased levels of appetite-stimulating neuropeptides such as neuropeptide Y (NPY) and agouti-related peptide (AgRP), which reduces energy expenditure, increases food intake, weight gain, and hyperlipidemia." (PMID 37425327, 2023).
Impaired glucose tolerance (2 papers, 2022 to 2025). An abnormal resistance to glucose, i.e., a reduction in the ability to maintain glucose levels in the blood stream within normal limits following oral or intravenous administration of glucose. "Mice with AgRP-Raf1 overexpression exhibited significant weight gain, mild hyperphagia, increased adiposity, and impaired glucose tolerance." (PMID 40432214, 2025).
metabolic syndrome (2 papers, 2014 to 2021). A cluster of metabolic risk factors for CARDIOVASCULAR DISEASES and TYPE 2 DIABETES MELLITUS. "A recent study demonstrated that AgRP neurons are critical in mediating metabolic syndrome in ob/ob mice since ablation of Agrp neurons in leptin deficient (ob/ob) mice showed reduced food intake and improved glucose tolerance." (PMID 25538630, 2014).
schizophrenia (2 papers, 2015 to 2025). A major psychotic disorder characterized by abnormalities in the perception or expression of reality. "Compared with controls, asprosin-related AgRP levels were also found to be lower in patients with bipolar disorder, which has many structural and clinical aspects in common with schizophrenia, and this was interpreted as an indicator of impaired homeostasis." (PMID 40075879, 2025). "AgRP levels have been studied in patients with bipolar disorder, and many structural and genetic similarities with schizophrenia have been identified." (PMID 40075879, 2025). "The main objective of the present study was to find out whether there is a significant difference in fasting serum levels of AgRP peptide between patients with schizophrenia on clozapine monotherapy and age- and sex-matched healthy controls." (PMID 25034457, 2015).
Arthritis (1 paper, 2010). Inflammation of a joint. "In addition, food-restriction led to a more profound decrease of mRNA expressions for anorexigenic factors (POMC, CART, IL-1β) and marked increase of mRNA expressions for orexigenic factors (NPY, AgRP) compared to the other dietary regimes with or without arthritis." (PMID 20953376, 2010).
cognitive decline (1 paper, 2023). "Further research is needed to more thoroughly explore the complex interaction malocclusion-induced cognitive decline and AgRP signaling." (PMID 37168929, 2023). "The present study suggests that elevated cerebral AgRP signaling contributes to malocclusion-induced cognitive decline in adolescents, and the suppression of AgRP signaling can be a new therapeutic target against cognitive decline in occlusal disharmony." (PMID 37168929, 2023). "Thus, the AgRP signal may be a key mediator of malocclusion-induced cognitive decline." (PMID 37168929, 2023).
Cognitive impairment (1 paper, 2023). Abnormal cognition is characterized by deficits in thinking, reasoning, or remembering. "The cognitive impairment in NOR test correlated with mRNA expression of AgRP, not Ucn2, in the present study." (PMID 37168929, 2023).